ZNF644 (zinc finger protein 644)
Description:
May be involved in transcriptional regulation.
Synonyms: Zep-2; KIAA1221; BM-005; MGC60165; MGC70410; MYP21; NatF
Tractability: PROTAC: UniProt records ubiquitination sites on it; ubiquitination databases record sites on it; its protein half-life has been measured.
Gene: Protein-coding gene on chromosome 1 (90,915,298 to 91,022,376, reverse strand). Ensembl gene ENSG00000122482.
Subcellular location: Nucleus
Subcellular location (Human Protein Atlas): Vesicles
Gene Ontology:
Molecular function: DNA-binding transcription factor activity, RNA polymerase II-specific; RNA polymerase II cis-regulatory region sequence-specific DNA binding; transcription corepressor binding
Biological process: regulation of transcription by RNA polymerase II
Cellular component: nucleus
Genetic constraint (gnomAD): Loss-of-function variants: 16 observed, 108.62 expected, observed/expected ratio (o/e) 0.15, 90% interval 0.099 to 0.22. The upper end of that interval is the gene's LOEUF score, 0.22, which puts it in group 1 of 6, group 1 being the genes least tolerant of losing a copy. Missense variants: 1,318 observed, 1,617.7 expected, observed/expected ratio (o/e) 0.81, 90% interval 0.78 to 0.85. Synonymous variants: 539 observed, 563.61 expected, observed/expected ratio (o/e) 0.96, 90% interval 0.89 to 1.03.
Homologues: Orthologues: macaque ZNF644 (99% identical), chimpanzee ZNF644 (98% identical), dog ZNF644 (95% identical), guinea pig ZNF644 (90% identical), pig ZNF644 (90% identical), mouse Zfp644 (85% identical), rat Zfp644 (81% identical), tropical clawed frog znf644 (57% identical), zebrafish znf644b (27% identical), zebrafish znf644a (22% identical). Paralogues in human: ZBTB41 (10% identical), ZNF407 (8% identical), WIZ (8% identical), ZNF287 (8% identical), ZBTB17 (8% identical), ZNF777 (8% identical), ZNF572 (8% identical), ZKSCAN7 (7% identical), ZNF214 (7% identical), ZNF687 (7% identical), ZNF527 (7% identical), ZNF852 (7% identical), and 38 more.
Diseases named in the same sentence as ZNF644 in open-access papers:
ZNF644 is named in the same sentence as 9 diseases in open-access papers, as found by Europe PMC text mining. Sharing a sentence is not in itself a finding about the gene and the disease. The quoted sentences say what the papers report.
myopia (11 papers, 2011 to 2025). "Among them, ZNF644 was identified as a potential factor causing inherited myopia in different populations." (PMID 30834109, 2019). "Our findings prove that ZNF644/Zfp644 is involved in the development of high-myopia, indicating that mutations such as, Zfp644S673G and Zfp644Δ8 are causative for changes connected with the disease." (PMID 30834109, 2019). "Among the physical interactions identified, we functionally characterized the association of the C2H2-like ZF protein ZNF644, linked to high-grade myopia, with the HMTs G9a and GLP." (PMID 27546533, 2016). "Further investigations are needed to determine the precise role of ZNF644 (and impact of mutations associated with high-grade myopia) in controlling G9a/H3K9me2 during retinal growth and differentiation in adult stem cell populations." (PMID 27546533, 2016). "Herein we focused on investigating the role for ZNF644 variants in high-grade myopia in a United States (US) cohort." (PMID 22539872, 2012). "DNA from a case cohort of 131 subject participants diagnosed with high-grade myopia was screened for ZNF644 variants." (PMID 22539872, 2012). "Our study has identified two novel variants in ZNF644 associated with high-grade myopia in a US cohort." (PMID 22539872, 2012). "A recent study implicated zinc finger protein 644 isoform 1 (ZNF644) variants with non-syndromic high-grade myopia in a Chinese-Asian population." (PMID 22539872, 2012). "After we performed sequencing analysis of the exons in the ZNF644 gene in 300 sporadic cases of high myopia, we identified an additional five mutations (I587V, R680G, C699Y, 3′UTR+12 C>G, and 3′UTR+592 G>A) in 11 different patients." (PMID 21695231, 2011). "The clinical features of affected patients with a ZNF644 gene mutation in the 300 sporadic cases with high myopia." (PMID 21695231, 2011). "Mutations in zinc finger protein 644 isoform 1 (ZNF644) were identified as potentially responsible for the phenotype of high myopia." (PMID 21695231, 2011). "Nevertheless, the specific mechanism underlying the action of ZNF644 and its function in the pathogenesis of high myopia remains unclear." (PMID 40920702, 2025). "Some studies have pointed out that the aberrant expression of ZNF644 may be a potential pathogenic factor for rheumatoid arthritis and strong myopia." (PMID 34504527, 2021). "In this article, Tropepe, Emili, and colleagues show that ZNF644, encoded by a gene linked to high-grade myopia of unknown function, physically associates with the histone methyltransferases G9a and GLP to co-regulate H3K9me2-mediated silencing in vivo." (PMID 27546533, 2016). "Mutation screening of ZNF644 has successfully identified 2 novel missense variants (c.725C>T, c.821A>T) in two ethnicities within our US population, thus supporting the original report of a causal candidate gene for high-grade myopia." (PMID 22539872, 2012). "Summary of affected patients with ZNF644 variants in 131 high-grade myopia cases." (PMID 22539872, 2012). "Summary of variants identified in ZNF644 in 131 high-grade myopia cases." (PMID 22539872, 2012). "We therefore screened for ZNF644 mutations in a high-grade myopia USA population data set." (PMID 22539872, 2012). "The clinical features of the high myopia family 951 with a ZNF644 gene mutation." (PMID 21695231, 2011). "Given that ZNF644 is predicted to be a transcription factor that may regulate genes involved in eye development, a mutant ZNF644 protein may impact the normal eye development and therefore underlie the axial elongation of the eye globe in high myopia patients." (PMID 21695231, 2011). "Our results suggest that ZNF644 might be a causal gene for high myopia in a monogenic form." (PMID 21695231, 2011). "Given that ZNF644 is predicted to be a transcription factor that may regulate genes involved in eye development, mutation may cause the axial elongation of eyeball found in high myopia patients." (PMID 21695231, 2011).
myopia (continued). "Znf644 regulates H3K9-mediated gene silencing during neurogenesis and has been linked to autosomal dominant high-grade myopia." (PMID 33514542, 2021). "ZNF644 is associated with transcriptional repression as a part of the G9a/GLP complex, and mutations in this gene are responsible for a monogenic form of myopia." (PMID 32641122, 2020). "Genetic factors linked to high-grade myopia include mutations in the C2H2-like zinc finger (ZF) protein ZNF644, which segregates with autosomal dominant inheritance." (PMID 27546533, 2016). "Further study of the biological function of ZNF644 will provide insight into the pathogenesis of myopia." (PMID 21695231, 2011). "Given that ZNF644 is predicted to be a transcription factor that may regulate genes involved in eye development, a mutant ZNF644 protein may impact the normal eye development and therefore may underlie the axial elongation of the eye globe in high myopia patients." (PMID 21695231, 2011). "All these results point to the important regulatory role of ZNF644 in myopia development." (PMID 30834109, 2019). "Our results suggest that ZNF644 may play a role in myopia development." (PMID 22539872, 2012). "Taking in account that myopia is not a retina related disease, the mouse model provides better opportunities to study the molecular role of ZNF644 in human patients with inherited high myopia, then lower vertebrate model." (PMID 30834109, 2019).
acute kidney injury (1 paper, 2024). Sudden and sustained deterioration of the kidney function characterized by decreased glomerular filtration rate, increased serum creatinine or oliguria. "Circ_0114428 is located in chr:91403041-91447927-, and consists of exons 2–4 of zinc finger protein 644 (ZNF644), and the published data have confirmed its upregulation in the serum samples of septic acute kidney injury." (PMID 38297223, 2024).
breast carcinoma (1 paper, 2021). "High expression of ZNF644 might be associated with the radiosensitivity of breast cancer patients, and reciprocally, low expression of the other 3 genes (ZNF341, ZNF544, and ZNF653) marked patients in the radiosensitive group." (PMID 34504527, 2021). "Multivariate Cox regression analysis of the two databases showed that high expression of ZNF644 and low expression of ZNF341, ZNF541, and ZNF653 were associated with radiosensitivity of breast cancer." (PMID 34504527, 2021). "High expression of ZNF644 and low expression levels of the other 3 genes (ZNF341, ZNF541, and ZNF653) were related to the radiosensitivity of breast cancer." (PMID 34504527, 2021).
retinal dystrophies (1 paper, 2022). "Furthermore, 24 families had VUS, two families with variants in genes related to non-syndromic EoHM (SCO2 and ZNF644) and seven families with variants in genes associated with other retinal dystrophies (TRPM1, CACNA1F, KCNV2, RDH5 and MERTK)." (PMID 35457050, 2022).
ZNF644 also shares sentences with these, for which no sentence is quoted: cancer (1 paper); colorectal cancer (1); retinitis pigmentosa (1); rheumatoid arthritis (1); type 1 brittle cornea syndrome (1).